CTLA4 (cytotoxic T-lymphocyte associated protein 4)
Diseases named in the same sentence as CTLA4 in open-access papers (continued):
Sharing a sentence is not in itself a finding about the gene and the disease.
tumor (continued). "The proinflammatory capacity of peripheral lymphocytes, mainly their IFN-γ production, was suggested to be a predictive marker for inhibition of tumor progression and preferable survival outcomes following PD-1 or dual PD-1/CTLA-4 blockade." (PMID 36430552, 2022). "Activation of checkpoint cascades such as those controlled by PD-1 or CTLA4 can result in inactivation of tumor-specific T cells and immune evasion." (PMID 35884501, 2022). "Our work demonstrates that therapeutic targeting of tumor sialylation is effective in vivo and enhances the efficacy of PD-1 and CTLA-4 blockade." (PMID 36322632, 2022). "Another trial of nivolumab with CTLA4 monoclonal antibody ipilimumab showed an overall response rate of 6% (2 of 32 patients), despite substantial responses in tumor reduction on imaging (73.1% and 58.4%)." (PMID 35205740, 2022). "Based on the significant anticancerous potential of CTLA-4 blockade in tumor models (murine), anti-CTLA-4 antibodies were promoted for development." (PMID 35337133, 2022). "Accordingly, ICIs such as anti-CTLA-4, anti-PD-1, and anti-PD-L1 can attach to these co-inhibitory receptors, thereby reactivating the immune response against tumour cells." (PMID 35621637, 2022). "Even though γδ T cells can infiltrate tumor spheroids, they quickly show exhausted immunophenotypes by increased expression of CTLA‐4, PD‐1 and PD‐L1 with limited tumor killing capacity in the spheroids." (PMID 35731974, 2022). "For instance, melanoma B16-F10 tumor-bearing mice were treated with photon beam radiotherapy combined with anti-CTLA-4 antibody immunotherapy." (PMID 35425754, 2022). "PD-1 and CTLA-4 are predominantly expressed by tumor-infiltrating T cells and rarely by tumour-infiltrating NK cells." (PMID 35911673, 2022). "In medullary thyroid cancer, a cohort study of 200 patients revealed that Tim-3, CTLA4 and PD-1/PD-L1 are promising biomarkers for tumor recurrence." (PMID 36159789, 2022). "Drugs designed to block CTLA-4, PD-1, or the PD-1 ligands were shown to restore endogenous effector T-cell-mediated anti-tumor immunity." (PMID 36430552, 2022). "Administration of anti-CTLA-4 antibody gave rise to an enhanced density of tumor-infiltrating CD4 and CD8 T cells." (PMID 35392976, 2022). "Immunophenoscore (IPS) is of significant value in predicting response to anti-CTLA-4 and anti-PD-1 regimens, by quantifying the determinants of tumor immunogenicity and depicting the intratumoral immune landscapes and cancer antigenomes." (PMID 36159831, 2022). "The selective targeting of oncogenic signaling molecules and the tumor immune microenvironment molecules (i.e., PD1/PD-L1/cytotoxic T lymphocyte associated antigen-4, CTLA-4/NKp-46/CD16/CD28/CD80/IL-2/IL-6) were evaluated." (PMID 36547898, 2022). "Despite the lack of clinical relevance in some cases, the combined therapies of MEK inhibitors, with antibodies targeting PD-1, PD-L1, or CTLA-4, have been explored and demonstrated to exert higher anti-tumor effects than monotherapies." (PMID 35159208, 2022). "In TME, certain tumor ligands bind to inhibitory molecules on T cells, such as CTLA-4, PD-1, TIM-3, and LAG-3 and others, which in turn produce immune-suppressive mediators, leading to the failure of cancer elimination." (PMID 35655158, 2022). "A combination approach incorporating anti-CTLA-4 or anti-TIM-3 further improved efficacy by increasing tumor immunogenicity and activating antitumor adaptive immune responses." (PMID 35688558, 2022). "Intriguingly, we found that PIC significantly improved the tumor response and animal survival when combined with RT + anti-CTLA-4, compared to RT + anti-CTLA-4 alone." (PMID 35999216, 2022). "Except for tumor-infiltrating lymphocytes, tumor mutational burden (TMB) and immune checkpoints, such as PD-1, PD-L1, and CTLA4, have been developed to predict immunotherapy." (PMID 36704336, 2022). "In the tumor microenvironment, overexpression of CTLA-4 on Treg leads to the downregulation of immune responses." (PMID 35758066, 2022).
tumor (continued). "Mice treated with combination anti-CTLA-4 and anti-PD-1 present with elevated levels of IL-12 in tumour free tissues, an activated MHCIIhigh phenotype of KCs and an increase in liver neutrophils." (PMID 35454819, 2022). "Anti-CTLA-4-mediated anti-tumor activity was positively dependent on Fc-mediated effector functions, such as antibody-dependent cell-mediated cytotoxicity (ADCC) and complement-dependent cytotoxicity (CDC)." (PMID 35237846, 2022). "The most clinically developed are those directed against PD-1, PD-L1 and CTLA4, with their use being widely accepted in several neoplastic diseases." (PMID 35327339, 2022). "Subcutaneous KPAR tumours responded toanti-CTLA4 but were refractory to anti-PD-1, as observed in an immunogenic melanomamodel." (PMID 35930804, 2022). "According to recent studies, ferroptosis can regulate the anticancer activity of CD8+ T cells via increasing tumor cell sensitivity to PD-1/PD-L1 or CTLA-4 blocking therapy." (PMID 36160009, 2022). "Several data generated from our tumor cohort suggest a possible biological relevance of CTLA-4+ lymphocytes." (PMID 35091676, 2022). "Researchers are trying to enhance the efficacies of tumor vaccines to induce antitumor immune responses by clearing suppressive cells, including Tregs, or blocking immunosuppressive pathways using the CTLA-4 antibodies." (PMID 35909469, 2022). "For the tumor cells, there were 2 (25%, PD-L1), 0 (0%, PD-1), 1 (13%, CTLA-4), 0 (0%, IDO) cases which showed positive IHC staining." (PMID 36104728, 2022). "Compared to the isotype control, the low-salt diet, when combined with anti-CTLA4 mAb, induced significant inhibition in tumor progression kinetics, thus suggesting that the LS diet did not impact the inflammatory activation of tumor infiltrating CD4+T cells." (PMID 35741331, 2022). "Transduction of a CTLA-4:CD28 CSR into tumor-specific T cells, resulted in elevated IFN-γ and IL-2 production and enhanced antitumor effect without systemic autoimmunity." (PMID 35432319, 2022). "ICIs unleash immune brake responses and effectively inhibit tumor immune escape by targeting programmed cell death 1 (PD-1) and its ligand (PD-L1), lymphocyte-activating gene-3 (LAG3), cytotoxic T lymphocyte-associated antigen-4 (CTLA-4), and other targets." (PMID 35488243, 2022). "Ipilimumab is a fully human mAb against CTLA-4 that achieves anti-tumor effects by binding to CTLA-4 and blocking its action with the B7 molecule." (PMID 36313314, 2022). "Immunohistochemistrystaining demonstrated that both anti-PD-1 and anti-CTLA-4 therapy increased theinfiltration of CD8+ T cells into the tumour, however this increase was greaterin anti-PD-1 treated mice." (PMID 35930804, 2022). "ALPN-202 had greater anti-tumor efficacy than either antibody alone and this activity was slightly potentiated when combined with anti-CTLA-4 mIgG2b." (PMID 35379805, 2022). "The model was further validated by the relative concordance of the simulated cancer cell decline with the tumor-killing performance of CTLA-4 blockade (compare the final population of tumor cells in anti-PD-1 and anti-CTLA-4 treatments, yellow curve)." (PMID 36428963, 2022). "With higher affinity for B7 than CD28, excessive activation of the CTLA4 pathway leads to a decline in immune function and subsequent immune escape of tumor cells." (PMID 36042469, 2022). "Tumor-infiltrating Tregs generally express higher levels of cell surface molecules associated with T cell activation, such as CD25, CTLA-4, PD-1, LAG3, TIGIT, ICOS, 4-1BB, OX-40, and GTFR." (PMID 34417572, 2022). "In the TME, receptors of PD-L1 and CD80 expressed by tumor cells or tumor-related immune cells can interact with PD-1 and CTLA-4 expressed by CD8 T cells, respectively, to impair CD8 T cell function." (PMID 35265130, 2022).
tumor (continued). "This inhibitory effect can be reversed with CTLA-4 blockade restoring, in part, the T-cell ability to proliferation in the presence of dexamethasone, and this enhanced survival in tumor-bearing mice." (PMID 35203636, 2022). "In 2012, Mike Dustin’s lab reported the effects of anti-CTLA-4 antibody on tumor growth and on T-cell motility in tumors." (PMID 35681548, 2022). "Expression of PD-1 and CTLA-4 were compared between tumor and normal tissue samples in UCEC patients." (PMID 35719911, 2022). "PD-1 and CTLA4 are two well-known immune checkpoints through which cancers prevent the immune system from recognizing and attacking tumor cells." (PMID 36276141, 2022). "The administration of anti-CTLA-4 siRNA-loaded NPs into CT26 and 4T1 tumor-bearing mice led to the downregulation of CTLA-4 on tumor-infiltrating T lymphocytes." (PMID 36015348, 2022). "In recent years, tumor immunotherapy such as anti-PD-1/PD-L1/CTLA-4 monoclonal antibody and chimeric antigen receptor T-cell (CAR-T) immunotherapy has extensively been attentioned as an important part of combined therapy." (PMID 36585688, 2022). "Given the complexity of tumor microenvironment and regulation of immune response, combination therapy is proposed, especially when the combination of anti-PD-1 and anti-CTLA4 presents promising efficacy on rGBM." (PMID 35135556, 2022). "In contrast, the 4T1 tumor–bearing mice showed complete progression upon anti–PD-1 plus anti–CTLA-4 treatment, which we considered to represent a model of true tumor progression." (PMID 35788116, 2022). "Immune checkpoint inhibitors (ICIs), such as those targeting PD-L1, PD-1, and cytotoxic T lymphocyte-associated antigen-4 (CTLA-4), have been investigated across multiple tumor types and have shown significant benefits in clinical studies." (PMID 36266384, 2022). "Side-by-side comparison of tumors responding to anti-PD1 versus anti-CTLA4, showed differences in response kinetics and distinct changes in response biomarkers, both local (tumor contexture) and systemic (circulating T-cell subsets)." (PMID 36230753, 2022). "It is well known that in the field of tumour immunotherapy, five immune checkpoints, namely, PD-1, CTLA-4, Tim-3, LAG-3, and TIGIT, have inhibitory effects on T-cell proliferation." (PMID 36110204, 2022). "It has been reported that the responsiveness of tumor to PD-1 plus CTLA-4 dual checkpoint blockade can be improved by inhibiting NETs." (PMID 35252353, 2022). "In contrast to subcutaneous tumours, orthotopic tumoursresponded to both anti-CTLA-4 and anti-PD-1 monotherapies, resulting in asignificant increase in the survival of tumour-bearing mice." (PMID 35930804, 2022). "Another phase III Chinese trial is exploring the same outcomes for trans-arterial/intratumoral infusion of anti-PD-1/PD-L1 antibodies and/or the anti-CTLA-4 antibody ipilimumab for several tumor types and includes an advanced HCC cohort (NCT03755739)." (PMID 36139683, 2022). "In particular, the CTLA-4 and PD-1 mechanisms are the top two representative immune checkpoint pathways, which negatively mediate the immune characteristic of T cells during tumor immunity." (PMID 36428755, 2022). "We found increased PD-L1 and CTLA-4 expression in local tumour tissues after oncolytic virus treatment." (PMID 34561555, 2022). "Clinical research has demonstrated that tumor growth and aggressiveness are directly correlated with CTLA-4 expression in GBM." (PMID 35954362, 2022). "Although activating T-cells is regarded as the primary anti-tumor mechanism of anti-CTLA-4 therapies, mounting evidence in the literature suggests targeting intra-tumoral Tregs as the primary mechanism of action of these agents." (PMID 35326731, 2022). "CTLA-4 can reduce the activation of T cells by generating inhibitory signals, thereby attenuating the anti-tumor immune response." (PMID 35874717, 2022).
tumor (continued). "Of note, radiotherapy, anti-CTLA-4 antibody, and anti-PD-L1/PD-1 antibody promote tumor immune response with distinct mechanisms." (PMID 35371055, 2022). "Hypomethylation of CTLA-4 and PD-1 in tumor tissues compared with matched controls was reported in NSCLC patients, leading to high expression." (PMID 35884355, 2022). "Multiple studies indicate that anti-tumor responses by PD-1/PD-L1 ICB are superior to CTLA-4 ICB and result in less toxicity." (PMID 35651800, 2022). "The anti-tumor mechanism of these anti-CTLA-4 mAb was first attributed to preventing interaction of CTLA-4 with its ligand B7 allowing APCs to present antigens and activate anti-tumor T cells response." (PMID 35874729, 2022). "In the present study, to interrogate the Fc-independent function of anti-CTLA-4 antibodies in promoting anti-tumor activity, we generated two types of anti-CTLA-4 antibodies with or without Fc effector functions." (PMID 35237846, 2022). "OX40L followed a similar trend to CTLA4 in which high expression of OX40L was correlated with higher BCRF survival in tumor-adjacent stroma cells, but shorter BCRF survival in tumor cells." (PMID 36230846, 2022). "Further emphasizing the potential interaction among diverse costimulatory and inhibitory pathways are observations from preclinical studies demonstrating that efficacy of anti-CD137, anti-GITR, and anti-CTLA-4 required CD226 for anti-tumor activity." (PMID 35263569, 2022). "For example, researchers have constructed an NP that combines an anti-cytotoxic T lymphocyte-associated protein 4 (anti-CTLA-4) monoclonal antibody and mRNA encoding tumor antigen MUC1 for enhancing anti-tumor benefits." (PMID 35664731, 2022). "Targeting with PD-1, PD-L1, or CTLA-4 reverses the enervation of cytotoxic T lymphocytes, thereby leading to tumor cell elimination via the induction of the normal functioning of T cells." (PMID 35337133, 2022). "In the mice model inoculated in this cancer cell line, the synergistic effects of anti CTLA-4 and PARPis have better anti-tumor results than any single drug, and the mice in this groups have the highest survival rate." (PMID 35281059, 2022). "A recent in vitro study demonstrated that immune checkpoint therapy with IL-18 combined with anti-PD-L1 or anti-CTLA4 inhibited tumor progression." (PMID 36552744, 2022). "In combination, MUC1 mRNA nanovaccine plus anti-CTLA-4 mAb appeared more effective than either nanovaccine or anti-CTLA-4 mAb alone at increasing level of apoptosis in tumor cells." (PMID 34875483, 2022). "In clinical trials, NCT04336241, a genetically modified HSV-1 expressing anti-cytotoxic T-lymphocyte associated protein 4 (anti-CTLA-4) antibody, is being evaluated to directly destroy tumors and generate an anti-tumor immune response." (PMID 35681776, 2022). "In a follow-up study, it was elucidated that the activity of anti-CTLA-4 is mediated via selective Treg depletion within the tumor site." (PMID 36159809, 2022). "Immune checkpoint blockade, with the use of antibodies targeted against programmed death-1 (PD1), its ligand (PD-L1), or cytotoxic T lymphocyte-associated protein-4 (CTLA-4), leads to disinhibition of T-cells, allowing them to target tumor cells effectively." (PMID 36612116, 2022). "We have previously reported that mRNA level of CTLA-4 in tumor tissues was increased in advanced stages of CRC, suggesting their possible effects in CRC progression." (PMID 35655158, 2022). "The engagement of CTLA-4 in T cells during the induction phase of an anti-tumor immune response impedes T cell activation by inhibition of the co-stimulation signal, leading to anergy." (PMID 35205703, 2022). "Their mechanism of action is to selectively restore and normalize the body's immune reponses by disrupting the immunosuppressive signals mediated by PD-1, PD-L1 and CTLA-4 in the tumor microenvironment." (PMID 36119464, 2022).
tumor (continued). "The TIDE prediction score can be interpreted as a z-score; a higher value indicates a higher potential of tumor immune evasion and a lower likelihood of benefitting from anti-PD-1/CTLA-4." (PMID 35631431, 2022). "One of the best-known examples is immune checkpoints, such as CTLA-4 and PD-1, which are exploited by tumor cells." (PMID 36009389, 2022). "In the Hu-HSC model of EBV-associated lymphoma, the combination of PD-1 and CTLA-4 inhibitors can effectively inhibit the growth of EBV-induced diffuse large B-cell lymphoma and the anti-tumor effect is better than that of monotherapy." (PMID 36012461, 2022). "Cytotoxic T lymphocyte-associated protein 4 (CTLA4) and programmed cell death ligand 1 PD-L1 (known as CD274) are immune checkpoint proteins expressed on tumor cells and tumor-infiltrating immune cells." (PMID 36230798, 2022). "The tracer was tested in mice xenografted with CT26 cancer cells, which showed that the peptide is eliminated renally and that the uptake in the tumor is predictive for therapy response with anti-PD-1 and anti-CTLA-4 combination therapy." (PMID 35625811, 2022). "Immune checkpoint inhibitor (ICI) can promote the immune system to recognize and suppress basic molecular targets of tumour cells such as PD‐1, CTLA‐4, and PD‐L1." (PMID 36083778, 2022). "Collectively, these findings show that tumor-expressed B7x provides resistance to anti-CTLA-4 therapy in Treg-dependent manner." (PMID 35523809, 2022). "Additional inhibition of the CTLA-4 pathway, on the other hand, causes increased activation of CD8-positive cells in lymph nodes and tumor cells." (PMID 35954441, 2022). "In fact, the CTLA-4 and PD-1/PD-L1 blockade was capable of restoring the host’s T cell-mediated immune system response, suppressed by the tumour." (PMID 36551630, 2022). "ICOS/ICOSL and CD28/B7-1/B7-2 are T cell co-stimulators and CTLA-4 is an immune checkpoint inhibitor that play critical roles in the pathogenesis of neoplasia." (PMID 36618349, 2022). "In the field of immunotherapy, current strategies mainly include blocking immune checkpoints such as PD-1 and CTLA-4 by antibodies or small-molecule inhibitors, thereby “re-firing up” the anti-tumor immune response." (PMID 36439090, 2022). "Nanomedicines derived from anti-CTLA-4 and anti-PD-L1 antibodies can inhibit tumor growth and reduce adverse effects." (PMID 36618938, 2022). "Following these proofs-of-concept experiments, we will now look for the effect of an immunotherapy anti-PD-1 or anti-CTLA-4 to monitor the impact on tumor cell immunotoxicity after adding autologous lymphocytes." (PMID 36654822, 2022). "The overexpression of PD-L1 and CD80/CD86 on tumor cells, which can respectively bind to PD-1 and cytotoxic T lymphocyte antigen 4 (CTLA4), results in the inhibition of T cell activation." (PMID 36013050, 2022). "The POC of ICI, i.e., anti-PD-1, anti-PD-L1 and anti-CTLA-4 antibodies, which reverse cancer immunosuppression and promote anti-tumor immune responses in several cancer types, were first demonstrated by using these mouse models." (PMID 35228603, 2022). "Combination therapies targeting the PD-1 and CTLA-4 immune checkpoints have shown the greatest therapeutic efficacy in improving the effector function of tumor-specific T cells." (PMID 36428613, 2022). "Based on transcription profiles of patients, tumor immune evasion capacity is assessed by TIDE, which represents the degree of tumor immune dysfunction and exclusion, indicating the response for anti-PD-1/PD-L1 and anti CTLA-4 therapies." (PMID 36406134, 2022). "The (PDT + CTLA-4)-gel multi laser treatment also induced more tumor neo-antigen (ADPGK and RPL18)-specific CD8+ T cells than the control group." (PMID 35974207, 2022). "There was an increase in MHC-I and PD-L1 expression on tumor cells, particularly in the anti-CTLA4 and combined immunotherapy cohorts." (PMID 36230753, 2022).